IL17A (interleukin 17A)
Diseases named in the same sentence as IL17A in open-access papers (continued):
Sharing a sentence is not in itself a finding about the gene and the disease.
bronchiectasis (9 papers, 2015 to 2025). Segmental, irreversible dilation of the bronchial tree resulting in the accumulation of secretions which leads to obstruction. "Compartmentalization of IL-17A production (luminal vs. epithelial) in these subjects with established bronchiectasis also explains the apparent discrepancy between elevated protein levels of IL-17A in BALF but not gene expression in biopsies." (PMID 25822228, 2015). "Th17 pathway cytokines were quantified in bronchoalveolar lavage fluid (BALF), and gene expression of IL-17A, IL-1β, IL-8 and IL-23 determined from endobronchial biopsies (EBx) in 41 stable bronchiectasis subjects and 20 healthy controls." (PMID 25822228, 2015). "Patients with bronchiectasis may benefit from IL-17a monitoring and from novel therapies aimed at clearing or reducing systemic inflammation that could increase the risk of subsequent infection and inflammation." (PMID 32823681, 2020). "Luminal neutrophils might be expected to be a relatively much greater source of IL-17A in old subjects with stable but established bronchiectasis, while mucosal IL-17A appears to predominate in childhood bronchiectasis subjects with earlier infection." (PMID 25822228, 2015). "The current data demonstrate highly significant increases in all Th17 pathway-associated chemokines and cytokines measured in the airways of adult bronchiectasis subjects, including pathway effectors (IL-17A, IL-6, IL-8 and TNF-α) and regulators (IL-1α, IL-1β, IL-6 and IL-23)." (PMID 25822228, 2015). "BALF levels of all Th17 cytokines (median (IQR) pg/mL) were significantly higher in bronchiectasis than control subjects, including IL-17A (1.73 (1.19, 3.23) vs. 0.27 (0.24, 0.35), 95% CI 1.05 to 2.21, p<0.0001) and IL-23 (9.48 (4.79, 15.75) vs. 0.70 (0.43, 1.79), 95% CI 4.68 to 11.21, p<0.0001)." (PMID 25822228, 2015). "However multivariate analyses did not identify any relationships between either of these variables and BALF IL-17A levels, with presence of bronchiectasis the only variable that predicted IL-17a levels." (PMID 25822228, 2015). "Our results suggest relatively greater importance of the neutrophil-related mediators IL-8 and IL-1α, than IL-17A, in adult non-CF bronchiectasis airway mucosal pathophysiology." (PMID 25822228, 2015). "Therefore, we aimed to evaluate acute systemic levels of proinflammatory cytokines (IL-17a, IL-1β, IL-8, and tumor necrosis factor alpha (TNF-α)) and high-sensitivity C-reactive protein (hsCRP) during bronchiectasis exacerbations and follow-up (days 30 and 60)." (PMID 32823681, 2020). "In CF children, elevated BALF IL-17A levels at baseline were associated with subsequent acquisition of Pseudomonas aeruginosa infection, and increases in cells staining positive for IL-17 have been identified in airway mucosal biopsies from both CF and non-CF bronchiectasis children." (PMID 25822228, 2015). "However, while gene expression of both IL-1β and IL-8 was significantly upregulated in the bronchial mucosa of non-CF bronchiectasis subjects, IL-17A was not, possibly reflecting the scarce relative abundance of the cells of origin in the mucosa." (PMID 25822228, 2015). "Hence, we speculate that neutrophils are the primary source of airway IL-17A in the chronic airway inflammation characterizing adult non-CF bronchiectasis." (PMID 25822228, 2015). "However, in contrast to the recent publication in children with non-CF bronchiectasis, adults with established disease did not demonstrate significantly increased expression of IL-17A in endobronchial biopsies (assessed by gene expression rather than immunohistochemistry)." (PMID 25822228, 2015). "The current study confirms, for the first time, significant airway luminal activation of the Th17 pathway in established adult non-CF bronchiectasis, in particular demonstrating significant elevations of BALF IL-17A and IL-23." (PMID 25822228, 2015).
brucellosis (9 papers, 2013 to 2025). Brucellosis is a bacterial infection that spreads from animals to people via unpasteurized dairy products or by exposure to contaminated animal products or infected animals. "IL-17A has been associated with chronic pain, similar to IL-6, and might explain the presence of pain in acute and chronic brucellosis." (PMID 38794208, 2024). "The expression of IL-17A in patients with brucellosis is higher than that in healthy controls." (PMID 31467933, 2019). "Although both IL-17A and IL-17F are cytokines mainly secreted by Th17 cells, the expression of IL-17A and IL-17F in patients at different stages is not consistent, suggesting that they may play different roles in regulating the immune mechanism of brucellosis." (PMID 31467933, 2019).
Chlamydia infection (9 papers, 2011 to 2024). "Previous studies have identified Chlamydia-specific IFN-γ+IL-17A+ CD4 T cells in the FRT following Chlamydia infection or vaccination." (PMID 38271477, 2024).
chronic GVHD (9 papers, 2014 to 2025). "MAIT cells (CD3+CD161+Vα7.2TCR+) were the only CD8+ IL-17A-secreting T cell subset following G-CSF mobilization, and the proportions of RORγt-expressing or coexpressing IFN-γ/IL-17A associated with chronic GVHD in MAIT cells were further enhanced with G-CSF mobilization." (PMID 36052080, 2022). "We therefore examined the differentiation of IL-17A-producing CD4+ (Th17) and CD8+ (Tc17) T cells, which contribute to the development of fibrotic acute and chronic GVHD, especially in the skin." (PMID 38828727, 2024).
dementia (9 papers, 2013 to 2025). Loss of intellectual abilities interfering with an individual's social and occupational functions. "Our study aimed to evaluate inflammatory cytokines CSF IL-6 and IL-17A in patients with vascular cognitive impairment of the subcortical small-vessel disease subtype in order to discriminate vascular from neurodegenerative causes of dementia, particularly AD." (PMID 40150012, 2025).
Encephalopathy (9 papers, 2018 to 2024). Encephalopathy is a term that means brain disease, damage, or malfunction. "For example, Tfl-deficit mice prolonged encephalitic inflammation caused by the experimental animal encephalopathy model failing to degrade IL-17a in CNS-infiltrated lymphocytes." (PMID 37304286, 2023). "IL-17, IL-6, IL-21, IL-22, IL-23, and TNF-α are inflammatory cytokines generated by Th17 cells, of which IL-17A is the most important cytokine in Th17-mediated encephalopathy." (PMID 36176437, 2022).
histoplasmosis (9 papers, 2016 to 2023). A disease caused by the fungus Histoplasma capsulatum. "Gal-3 was also detrimental to the host resistance against histoplasmosis by negatively regulating IL17-A responses, which was attributed to inhibition of the IL-23/IL17 axis in dendritic cells." (PMID 29213074, 2017). "Significant differences in the median values of IL-1β, TNF-α, IFN-γ, IL-18, IL-17A, IL-33, IL-13, and CXCL8 were reached in all the groups studied, suggesting that these cytokines play a role in the inflammatory processes associated with histoplasmosis and pneumocystosis." (PMID 34829225, 2021). "Significant differences in median values of SP-A, IL-1β, TNF-α, IFN-γ, IL-18, IL-17A, IL-33, IL-13, and CXCL8 were found among all the groups studied, suggesting that these cytokines play a role in the local inflammatory processes of histoplasmosis and pneumocystosis." (PMID 34829225, 2021). "The highest IL-17A levels present in patient groups with histoplasmosis, mainly in the Non-HIV-Hc group, are in accordance with previous reports on the participation of Th17 response in experimental histoplasmosis infection." (PMID 34829225, 2021).
IgA nephropathy (9 papers, 2017 to 2024). "In our case, the activity of IgA nephropathy was exacerbated by anti-TNFα therapy but was improved by the combination of corticosteroids, tonsillectomy, and an IL-17A inhibitor against the original disease." (PMID 32842976, 2020). "Therefore, IL-17A is considered as a potential biomarker of IgA nephropathy." (PMID 35725391, 2022).
latent infection (9 papers, 2010 to 2025). "Throughout the acute and latent infection, we observed a downregulation of IL-17A expression on ABCs." (PMID 36477199, 2022).
nasopharyngeal carcinoma (9 papers, 2011 to 2025). A carcinoma arising from the nasopharyngeal epithelium. "In this study, we explored the effect of interleukin-17A (IL-17A) on the migration and invasion activity of nasopharyngeal carcinoma (NPC) cell lines and account for related mechanisms." (PMID 25244643, 2014). "However, it was also recently reported that IL-17A induces the proliferation of nasopharyngeal carcinoma cell lines." (PMID 31083515, 2019). "In the tumour microenvironment of human nasopharyngeal carcinoma, IL‐17A mediates AKT1 acetylation via p300, activating the Akt signalling pathway and stimulating the proliferation of nasopharyngeal carcinoma cells." (PMID 39778006, 2025).
pancreatitis (9 papers, 2016 to 2025). Inflammation of the pancreas. "We observed Ly6G-expressing neutrophil granulocytes to be the main infiltratingimmune cell population in IL-17A-induced pancreatitis." (PMID 26964500, 2016). "Neutrophil accumulation incaerulein-induced pancreatitis is fundamentally different from neutrophilaccumulation in intraductal aggNETs in the IL-17A-induced model." (PMID 26964500, 2016). "In recent years, IL-6 and IL-17A have become hot research topics, with several studies suggesting that they are involved in the process of AP and can be used in clinical practice to predict the severity of pancreatitis." (PMID 39296668, 2024). "Lymphocytes may, however, constitute acellular source of IL-17A, in other models of pancreatitis or humanpathophysiology." (PMID 26964500, 2016). "IL-17A delivery in these strains revealed thatneither IL-6 nor signalling via these TNF or IL-1 receptors were required forthe development of pancreatitis: all mice tested developed neutrophil aggregatesand pancreatitis in response to IL-17A in a similar manner." (PMID 26964500, 2016). "IL-17A induces the neutrophil chemoattraction to the secretory ducts of the pancreas, and the subsequent formation of aggregated neutrophils hampers the secretory flow and induces a focal pancreatitis due to ductal occlusion, which strongly determines the severity of CP." (PMID 32266154, 2020). "As expected, and incontrast to the IL-17A challenge model, intraductal aggNETs containing H3citwere absent in caerulein-induced pancreatitis." (PMID 26964500, 2016).
paracoccidioidomycosis (9 papers, 2014 to 2025). A systemic fungal infection caused by Paracoccidioides brasiliensis that is most often seen in immunocompromised patients. "The production of Th17-associated cytokines (IL-6, IL-23, and IL-17A) during experimental paracoccidioidomycosis was analyzed." (PMID 33668671, 2021).
Thrombocytopenia (9 papers, 2017 to 2025). A reduction in the number of circulating thrombocytes. "Leukopenia, thrombocytopenia, erythrocytopenia, and bone marrow cell depletion are caused by radiation therapy associated with hemorrhage, which increases the production of IL-1, IL-6, and IL-17A in the IL-17 signaling pathway and increases BMS." (PMID 37654610, 2023). "Triple-high IFN-λ1, IL-17A, and IL-23 patients displayed a higher frequency of thrombocytopenia." (PMID 28619037, 2017). "Severe thrombocytopenia was positively correlated with IL-4, CXCL10, IL-6, IL-10 and IFN-γ levels, renal dysfunction was related to an increase in IL-2, IL-1β, IL-17A and IL-8, and hepatic impairment with CXCL10, MCP-1, IL-6 and IFN-γ." (PMID 36178979, 2022). "Second, the mechanism by which IL-17A regulates coagulation and its effect on thrombocytopenia is not clear." (PMID 37063881, 2023). "Thus, thrombocytopenia and development of SDD could be attributed to IL-17A production in DV-/ZV+ patients." (PMID 37943879, 2023).
urinary tract infection (9 papers, 2011 to 2025). "Collectively, we concluded that the increased Intestinibacter abundance was closely associated with the pathogenesis of urinary tract infections in patients with stones, and it has been shown that IL-17A was significantly elevated in patients with urinary tract infections." (PMID 40093533, 2025). "Urolithiasis with gut dysbiosis developed a higher incidence of urinary tract infections, which may be associated with the increasing of Intestinibacter and affect the expression of IL-17A by translational, ribosomal structural and biosynthetic function." (PMID 40093533, 2025). "In our study, by combining metabolism, gut bacteria composition and urinary tract infections, we demonstrated that the enrichment of Intestinibacter may affect IL-17A and thus result to a greater susceptibility to urinary tract infections in patients with stones." (PMID 40093533, 2025). "Hence, we showed that stone patients with disordered gut microbiota tended to be exposed to urinary tract infections, which may be associated with the Intestinibacter and IL-17A." (PMID 40093533, 2025). "Bladder epithelial cells can induce IL-17A production in bladder ILC3s during urinary tract infection through the release of IL-1β, and IL-17A subsequently mediates neutrophil recruitment to confer protection against UPEC." (PMID 41467015, 2025). "This indicated that the IL-17A can well predict the occurrence of urinary tract infection in urolithiasis, and the infection prediction using the abundance of Intestinibacter, is supported but less efficient." (PMID 40093533, 2025). "Consistent with this, studies have shown that IL-17A−/− mice present a defective neutrophil and monocyte recruitment in model of urinary tract infection by uropathogenic Escherichia Coli." (PMID 30555461, 2018). "The link between IL-17A and E. coli pneumonia is supported by the findings that LPS activates IL-17A production in the lung and IL-17A −/− mice have increased E. coli burden in urinary tract infection." (PMID 22514650, 2012). "Future studies may be able to further elucidate the causality and related pathways of urolithiasis combined with urinary tract infection, intestinal flora, and IL-17A." (PMID 40093533, 2025). "The relationship between IL-17A and urinary tract infections has been proved in animal models." (PMID 40093533, 2025). "The area under the curve (AUC) for the fitting of urinary tract infection in stone patients with the IL-17A was 0.89, the AUC for the abundance of Intestinibacter was 0.66 and the AUC when combining the abundance of Intestinibacter and IL-17A was 0.89." (PMID 40093533, 2025). "Furthermore, we found that Intestinibacter might influence the development of urinary tract infections critically in patients with stones by affecting the expression and secretion of IL-17A." (PMID 40093533, 2025). "Therefore, we considered that Intestinibacter may induce the pathogenesis of urinary tract infection in stone patients by affecting the expression or secretion of IL-17A." (PMID 40093533, 2025). "Therefore, considering the correlation analysis of Intestinibacter was highly concordant with the baseline characteristics in terms of IL-17A, Intestinibacter may induce the pathogenesis of urinary tract infections in patients with stones by affecting the expression or secretion of IL-17A." (PMID 40093533, 2025). "Previous studies have also mentioned that serum levels of IL-17A were shown to be increased in patients with urinary tract infections compared with non-infection patients." (PMID 40093533, 2025).
vaginal infection (9 papers, 2011 to 2025). "While some studies suggest a protective function of IL-17A against C. albicans vaginal infections, others have reported that IL-17 signaling is dispensable in VVC (24, –, 27)." (PMID 41060043, 2025). "The second of these was assessed with a multi-analyte flow assay kit to determine the levels of IL-6, TNF-α, IL-1β, IL-10, IL-1α, IL-17a, MCP-1, and IFN-γ in the supernatant of cervical tissue homogenate of GrpE-immunized mice and control groups after vaginal infection." (PMID 32849509, 2020).
anterior uveitis (8 papers, 2018 to 2025). Inflammation of the iris and anterior chamber of the eye. "IL-17A levels were weakly correlated with disease activity and structural severity and were significantly lower in patients with a history of anterior uveitis." (PMID 40807227, 2025). "More evidence is received about the role of IL-17A in SpA pathogenesis: inflammation maintenance, syndesmophites formation and radiographic progression, enthesites and anterior uveitis development, etc.." (PMID 37238999, 2023). "Additionally, the observed inverse relationship between IL-17A levels and anterior uveitis represents a novel and unexpected finding that merits further mechanistic exploration, particularly in light of existing therapeutic paradigms targeting IL-17 in axSpA." (PMID 40807227, 2025). "IL-17A plays a key role in the pathogenesis of spondyloarthritis (inflammation maintenance, syndesmophites formation and radiographic progression, enthesites and anterior uveitis development, etc.)." (PMID 37238999, 2023). "Interestingly, we also observed lower IL-17A levels in patients with a history of anterior uveitis, a finding that has not been consistently reported previously." (PMID 40807227, 2025).
apical periodontitis (8 papers, 2017 to 2025). "Additionally, the cytokines TNFα, IL-21, IL-17A, and IFN-γ were associated with augmented transcriptional activity of MMP-1 in apical periodontitis, favoring its development." (PMID 31379856, 2019). "Therefore, we hypothesized that the use of NETs inhibitors or anti‐IL‐17A antibodies to suppress IL‐17A may disrupt this loop, thereby alleviating apical periodontitis and bone destruction." (PMID 41031144, 2025). "Moreover, the skewed distribution of Th17/Treg cells in the periapical bone region of OVX/periapical periodontitis rats was also rescued by the treatment of probiotics, as reflected by decreased number of IL‐17A+ cells and increased number of Foxp3+ cells per hpf." (PMID 34101283, 2021).
atopic asthma (8 papers, 2016 to 2024). An asthma that is characterized by symptoms that are triggered by an allergic reaction caused by inhaled allergens such as dust mite allergen, pet dander, pollen and mold. "To figure out why IL-17A only had an impact on neutrophilia in combination with atopic asthma, we analyzed the expression of the IL-17A receptor subunits A and C, which form a heterodimer to recognize IL-17A." (PMID 37443808, 2023). "It is now generally accepted that Th2 cells and Th17 cells significantly contributed to atopic asthma, hence we detected Th2-derived cytokines—IL-4, IL-5, IL-13, and Th17-derived cytokines—IL-17A in BALF." (PMID 33013383, 2020). "In addition, the frequency of circulation Th2 cells that produce both IL-17A and classical Th2 cytokines (IL-4, IL-5, and IL-13) is higher in patients with atopic asthma than healthy controls." (PMID 34344357, 2021).
B cell lymphoma (8 papers, 2011 to 2024). "In line with our data, a recent paper showed the effect of promoting growth of B cell non-Hodgkin lymphomas depended on IL-17A overexpression in NOD/SCID mice." (PMID 30305610, 2018).
cholestasis (8 papers, 2014 to 2024). Impairment of the bile flow caused by obstruction within the liver, or outside the liver in the bile duct system. "Abnormal expression of IL-6, IL-10, IL-17A, IL-17F, TGF-β1 and α-SMA are closely associated with the cholestasis." (PMID 28646179, 2017). "Thus, in the bile duct obstruction stage, IL-17A is probably predominantly produced by activated Th17 cells, rather than γδT cells." (PMID 26325187, 2015).
coccidiosis (8 papers, 2014 to 2023). A parasitic infection caused by Coccidia. "Moreover, our previous studies have indicated that Th17-related cytokines such as IL-17A and IL-17F, and IL-17 receptor signaling are involved in inflammation induced by coccidiosis, although the predominant protective response in coccidiosis is considered to be an IFN-γ-related Th1 response." (PMID 30972060, 2019).